GPX4 (glutathione peroxidase 4)
Diseases named in the same sentence as GPX4 in open-access papers (continued):
Sharing a sentence is not in itself a finding about the gene and the disease.
epilepsy (continued). "Patients with epilepsy exhibit lower levels of GPX4 and GSH compared to normal controls, and these alterations have been associated with ferroptosis." (PMID 37891735, 2023). "A marked dysregulation of 4-HNE, GSH, and GPX4 by measuring ferroptosis biomarkers in blood from 83 unrelated children with a clinical diagnosis of epilepsy and 44 age-matched controls confirms a crucial role for ferroptosis in epilepsy." (PMID 36062196, 2022). "The overload of 4-HNE and the decrease of GSH represent a highly toxic combination in epilepsy because of their direct (by covalent binding) and indirect (by providing the reaction substrate) abilities to respectively inhibit GPX4." (PMID 34439515, 2021). "Some studies have also found that animals with Trsp and Gpx4 knockout exhibit significant neurophenotypes, including hyperexcitability, spontaneous epilepsy, and ataxia." (PMID 33424539, 2020). "Evidence for a critical role of GPX4 in epilepsy has arisen from the results showing that GPX4 is a selenium-dependent enzyme for interneuron development and prevention of epileptic seizures." (PMID 31379480, 2019). "Additionally, another ferroptosis marker, GPX4, was significantly downregulated on the first and third days following KA‐induced epilepsy." (PMID 39957487, 2025). "This further supports the hypothesis that AST inhibits neuronal death in epilepsy by activating the Nrf2/GPX4 signaling pathway to inhibit ferroptosis." (PMID 39957487, 2025). "Likewise, we explored the level of GPx4, a crucial mediator of ferroptosis, using Western blotting on brain tissues from epilepsy and control groups." (PMID 38357854, 2024). "Furthermore, a partial inactivation of GPX4 activity has been recently unveiled in the blood of children with epilepsy." (PMID 37396923, 2023). "Patients with epilepsy show low levels of GPX4 and GSH compared to healthy controls." (PMID 34335189, 2021). "Therefore, we decided to analyze the GPX4 expression and activity in leukocytes of children with epilepsy." (PMID 34439515, 2021). "On the other hand, GPX4 may have neuroprotective functions, and the regulation of GPX4 might be a new strategy for the treatment of neurodegenerative diseases including epilepsy." (PMID 33424539, 2020). "Furthermore, GPX4 expression was decreased in epilepsy but was increased in nerve injury after the use of iron death inhibitors." (PMID 33424539, 2020). "Thus, we explored whether AST could inhibit ferroptosis via the Nrf2/GPX4 pathway to have a neuroprotective effect on epilepsy." (PMID 39957487, 2025). "Therefore, this study aims to investigate whether AST can alleviate neuronal ferroptosis in epilepsy by activating the Nrf2/GPX4 pathway, thereby exerting a neuroprotective effect." (PMID 39957487, 2025). "To determine the mechanism of miR-211-5p, we showed through WB or qRT-PCR that GPX4 was upregulated, but HO-1 and P-ERK/ERK were downregulated after induction of miR-211-5p in the epilepsy mouse model." (PMID 38191407, 2024). "Recent research showed that significant decrease in GSH levels, a reduction in the GPX4 activity, and an increase in LPO in the blood of children with epilepsy." (PMID 37755077, 2023). "Nonetheless, as the most important free radical scavenging compound and physiological regulator in ferroptosis, GPX4 and GSH may have key roles in attenuating oxidative stress and preventing neuronal death in epilepsy." (PMID 34335189, 2021). "Activation of the HIF-1α/H -1 pathway is evident as hippocampal neurons in epileptic animal models and epilepsy patients’ brain tissues show marked HIF-1α and HO-1 upregulation, positively correlating with ferroptosis markers like lipid peroxides, ACSL4 increase, and GPX4 inactivation." (PMID 40421132, 2025). "Thus, blocking P2RX7 might regulate GPX4/HO-1 axis by suppressing the MAPK-ERK pathway, participating in ferroptosis in epilepsy." (PMID 38191407, 2024).
epilepsy (continued). "However, whether GPX4 can be a putative target for reducing neuronal injury in epileptic brain, especially in PTE, is yet to be verified in animal models and cell epilepsy models." (PMID 33424539, 2020). "Another clinical study in pediatric epilepsy patients found elevated markers of ferroptosis in their peripheral blood, including increased levels of the lipid peroxidation byproduct 4-hydroxy-2-nonenal, partial inactivation of GPX4, and a significant decrease in GSH levels." (PMID 37876811, 2023). "Collectively, these findings imply that mitochondrial dysfunction due to low GPX4 and GSH levels during ferroptosis is a nonnegligible reason for cell damage in epilepsy." (PMID 37891735, 2023).
ischemia (21 papers, 2019 to 2026). A hypoperfusion of the BLOOD through an organ or tissue caused by a PATHOLOGIC CONSTRICTION or obstruction of its BLOOD VESSELS, or an absence of BLOOD CIRCULATION. "Other studies have shown that EA activates the Nrf2/SLC7A11/GPX4 antioxidant pathway, suppresses lipid peroxidation, preserves mitochondrial integrity, and attenuates ischemia mitochondrial integrity Nrf2/SLC7A11/GPX4 antioxidant pathway." (PMID 41561334, 2025). "Previous studies have indicated that the activation of GPR30 can inhibit ferroptosis through the Nrf2/GPX4 signaling pathway, thereby ameliorating ischemia-reperfusion injury in the brain." (PMID 40076648, 2025). "Injection of the SLC7A11 inhibitor Erastin reduced the expression of SLC7A11 and GPx4, indicating that 14 days of aerobic exercise can activate the Nrf2/SLC7A11/GPx4 pathway, thereby reducing sensitivity to ferroptosis in the ischemia–reperfusion brain model." (PMID 39315073, 2024). "Ferroptosis occurs via ROS-induced lipid peroxidation following ischemia and is conventionally blocked via the action of glutathione peroxidase 4 (GPX4)." (PMID 39037770, 2024). "The levels of GPX4 in normoxic rats significantly declined after 24 h ischemia/reperfusion when compared with the sham rats,whereas NBO alleviated the ischemia‐induced GPX4 decline." (PMID 35698913, 2022). "Together, these results suggested that NBO treatment retained the redox balance in astrocytes during the early phase of ischemia/reperfusion, by using the GPX4/NOX4 pathway." (PMID 35698913, 2022). "However, a study has shown that continuous treadmill exercise for 14 days, at 30 min per day and 10 meters/min, increased the expression of Nrf2, SLC7A11, and GPx4 in an ischemia–reperfusion brain model." (PMID 39315073, 2024). "Immunofluorescence detection results revealed differential expression patterns of GPX4 and ACSL4 in the peri‐infarct cortex and hippocampal CA1 region post‐ischemia." (PMID 40376919, 2025). "The levels of GPX4 and NOX4 from ischemic tissues of NBO and normoxic rats were measured following 90‐min ischemia/24‐h reperfusion using western blotting." (PMID 35698913, 2022). "Resveratrol can reduce intestinal ischemia-reperfusion injury by activating the SIRT3/FoxO3a pathway, increasing the expression of SOD2 and catalase, reducing ROS and LPO production, compensating for the GSH/GPX4 pathway and inhibiting ferroptosis." (PMID 37858064, 2023). "Similar to NF-κB, phosphorylated STAT3 not only inhibits ferroptosis in intestinal ischemia/reperfusion-induced acute lung injury by positively regulating SLC7A11, but also induces ferroptosis in hypertensive mice by inactivating the SLC7A11/GPX4 signaling." (PMID 37153794, 2023). "The present study showed that NBO maintained the balance of redox (elevating GPX4 and suppressing NOX4 expression), attenuated oxidase activity downstream (HO‐1) in ischemia‐affected astrocytes, and eliminated mitochondrial damage in the form of cytochrome c release into cytosolic fractions." (PMID 35698913, 2022). "Emerging studies have shown that capsiate, a metabolite of the gut microbiota, upregulates GPX4 expression by activating transient receptor potential cation channel subfamily V member 1 (TRPV1), thereby inhibiting ferroptosis and protecting the intestine from ischemia/reperfusion injury." (PMID 40335466, 2025). "Indeed, the changes seen for several proteins related to this process (ACSL4, TFRS, GPX4, etc.), as well as the increase seen for the final product of lipid peroxidation, MDA, were indicative of ferroptosis up-regulation after 21 days of FAL induced ischemia." (PMID 39004727, 2024).
leukemia (21 papers, 2022 to 2025). A malignant (clonal) hematologic disorder, involving hematopoietic stem cells and characterized by the presence of primitive or atypical myeloid or lymphoid cells in the bone marrow and the blood. "This decrease in GPX4 activity led to a decrease in the antioxidant capacity of leukemia cells and an accumulation of ROS, causing ferroptosis." (PMID 39397802, 2024). "Moreover, ALDH3A2 depletion caused ferroptosis in leukemia cells and acted synergistically with GPX4 inhibition." (PMID 39397802, 2024). "The combination of ML-385 with glutathione peroxidase 4 (GPX4) inhibitor synergistically targeted leukemia cells triggering ferroptosis." (PMID 39408587, 2024). "Not only classic ferroptosis inducers (e.g., system xc−/GSH/GPX4 inhibitors) but also natural compound derivatives and other small molecules are shown to induce ferroptosis as a mechanism of their anti-leukemia activities." (PMID 37190037, 2023). "The inhibition of ALDH3a2 induces ferroptosis and exerts synergistic anti-leukemia effects with GPX4 inhibition or standard chemotherapy with cytarabine plus daunorubicin in vivo." (PMID 37190037, 2023). "In rat leukemia cells, overexpression of GPX4 inhibits Cytochrome c release, caspase activation, NFB activation, and DNA cleavage." (PMID 36818670, 2022). "We therefore firstly assessed whether cell death at 72 hours was induced in leukemia cells following treatment with a knownferroptosis inducer and GPX4 inhibitor RSL3 in parallel to volasertib." (PMID 40382332, 2025). "Furthermore, we analyzed GPX4 levels from Leukemia Mile study, and found that GPX4 levels were higher in AML samples than in NCs." (PMID 38378601, 2024). "The results showed that GPX4 is generally highly expressed in leukemia cell lines." (PMID 38032290, 2023). "Thus, rhTPO suppressed GPX4 expression through blocking the interaction between EP300 and GPX4 gene promoter via associating with EP300 in leukemia cells." (PMID 35768562, 2022). "Accordingly, our data revealed that apigenin caused a large induction of ferroptosis in ALL cells, as evidenced by increased levels of peroxidized lipids and Fe2+, as well as reduced levels of SLC7A11 or GPX4, suggesting that ferroptosis might be relevant to the anti-leukemia activity of apigenin." (PMID 39866226, 2025). "Collectively, these results demonstrate that circulating EVs from AML patients may trigger CD34+ AML cells toward an increase in both mitochondrial potential and GSH levels, reducing ROS levels and showing a leukemia-dependent mechanism partially reverted by GPX4 inhibition." (PMID 39738118, 2024). "Baicalein is a potential anti-ferroptosis compound that increases GPX4 expression, significantly inhibits ferroptosis, and restores phagocytosis in THP-1 cells (a human leukemia monocytic cell line) in vitro." (PMID 38397379, 2024). "GCFN not only depletes intracellular GSH and GSH-dependent GPX4, inducing ferroptosis in AML cells through lipid peroxidation, but also prolongs the lifespan of mice in leukemia models with minimal side effects." (PMID 39060524, 2024). "As anticipated, DFX administration also yielded a significant augmentation in the mRNA levels of genes pertinent to ferroptosis, namely, NRF2, KEAP1, HO-1, GPX4, and SLC7A11, within the leukaemia cells of individuals with ALL." (PMID 38671872, 2024). "By using the EMBL-EBI bioinformatics website, GPX4 and AIFM2 expression levels were analyzed in leukemia cell lines." (PMID 38032290, 2023). "The significant changes of GPX4 and AIFM2 expression in transcription level between different types of leukemia and normal control." (PMID 38032290, 2023). "Future research should investigate whether targeting ferroptosis regulators, such as GPX4 and NFE2L2 (NRF2), could enhance the sensitivity of resistant leukemia cells to daunorubicin." (PMID 41360907, 2025).
leukemia (continued). "Although the functional consequences of this stratification are not clear in the context of actual ferroptosis induction, we reasoned that decreased GPX4, FTH1 and SLC7A11 levels might facilitate ferroptosis induction in leukemia cells." (PMID 40382332, 2025). "Multidrug-resistant (MDR) K562/adriamycin (ADM) leukemia cells have higher GSH levels and iron-regulatory protein 2 (IRP2), transferrin receptor, ferritin heavy chain 1 (FTH1), and GPX4 expression, which may enhance their antioxidantcapacity and protect K562/ADM cells from ferroptosis." (PMID 39060524, 2024). "There were many leukemia-related genes in the up-regulated genes of K1 group, such as UBB (P=1.56e-50), MIF (P=2.76e-50), DRAP1 (P=1.72e-49), RPS25 (P=1.9e-49), EIF3K (P=4.77e-49), SSNA1 (P=1.27e-48), GPX4 (P=3.01e-48), PHB2 (P=7.13e-48), NME2 (P=2.44e-47) or CFL1 (P=4.07e-47)." (PMID 36408189, 2022).
Alzheimer disease (19 papers, 2020 to 2026). A progressive, neurodegenerative disease characterized by loss of function and death of nerve cells in several areas of the brain leading to loss of cognitive function such as memory and language. "Overexpression of GPX enzymes such as GPX1 and GPX4 is thought to protect against neurodegenerative processes, including convulsive disorders, Alzheimer’s disease, and PD." (PMID 39273702, 2024). "Cluster 3: Keywords included Alzheimer’s disease, amyotrophic lateral sclerosis, cell death, lipid peroxidation, reactive oxygen species, glutathione, GPX4, iron metabolism, and iron overload." (PMID 39280701, 2024). "In a study examining Alzheimer’s disease, when GPX4 was knocked out in specific cerebral cortex and hippocampal neurons, mice exhibited significant cognitive disability in the water maze test and hippocampal neuron degeneration." (PMID 37266433, 2023). "Other studies have shown that decreased levels of GPx-4 lead to lower numbers of hippocampal neurons and astrocytes in adult mouse models of Alzheimer’s disease and that cell death due to decreased GPx-4 is a characteristic of ferroptosis." (PMID 35495915, 2022). "The antioxidant GPX4 has beneficial effects in a range of pathological conditions, such as neurodegeneration and Alzheimer’s disease." (PMID 31906464, 2020). "In addition, suppressing GSH and GPX4 expression levels is usually accompanied by the accumulation of Fe2+ and the activation of lipid peroxidation in Alzheimer’s disease (AD)." (PMID 36035135, 2022).
asthma (19 papers, 2014 to 2026). "ICGAC suppresses asthma-associated inflammatory and oxidative stress responses through the upregulation of GPX4, SLC7A11, and Nrf2 in lung tissue." (PMID 40430003, 2025). "Cigarette smoke, infection, and other factors that can lead to the decrease of GPX4 activity can cause the imbalance of lipid redox in epithelial cells, resulting in airway epithelial dysfunction and aggravating airway inflammation in asthma." (PMID 34402724, 2021). "Notably, GPX4 plays a central role in protecting cells against oxidative damage and ferroptosis by reducing membrane phospholipid peroxides—an important mechanism implicated in asthma pathogenesis." (PMID 41463538, 2025). "Here, we investigated the regulatory function of GPX4 in asthma airway epithelial cells using an OVA-induced murine model in conjunction with a lipopolysaccharide (LPS)-stimulated BEAS-2B cell system." (PMID 41735987, 2026). "Glutathione peroxidase 4 (GPX4), the key enzymatic suppressor of ferroptosis, has a role in asthma that remains insufficiently defined." (PMID 41735987, 2026). "In this study, we explored how ICGAC suppresses asthma-related inflammation and oxidative stress, specifically by upregulating GPX4, SLC7A11, and Nrf2 in lung tissues." (PMID 40430003, 2025). "Beyond the canonical GPX4/system Xc- axis, emerging research has revealed additional mechanisms that critically regulate ferroptotic sensitivity in asthma." (PMID 41573584, 2025). "The overexpression of METTL3 in asthma models helps to increase the m6A modification of GPX4, a key protein that protects cells from ferroptosis (a type of cell death)." (PMID 41008562, 2025). "Interleukin-33 (IL-33), an epithelial-derived alarmin upregulated in asthma, directly inhibits GPX4 expression—simultaneously exacerbating ferroptosis and promoting type 2 inflammation." (PMID 41573584, 2025). "These structural motifs mainly METTL3′s Rossmann fold and zinc finger (ZF) domains are functionally relevant to asthma, as they enable specific m6A deposition on epithelial transcripts such as GPX4." (PMID 41008562, 2025). "GPX4-induced iron death occurs to exacerbate the progression of asthma disease in humans, and inhibition of GPX4 gene expression attenuates bronchial epithelial cell damage and NA progression in mice." (PMID 39108751, 2024). "The mRNA and protein expressions of FTH1 and GPX4 were significantly increased in the lung tissues of the SC group compared with the asthma group (P<0.05)." (PMID 37970439, 2023). "In our study, we observed a decreased expression of FTH1 and GPX4 in asthma mice, indicating ferroptosis occurred in asthma." (PMID 37970439, 2023). "Additionally, BG-NPs reduced ferroptosis by inhibiting iron accumulation and upregulating GPx4 protein levels in the lung tissue, offering an innovative strategy for the clinical management of asthma." (PMID 39305381, 2025). "Considered together, m6A methylation may be involved in the mechanism of NA asthma by inducing the onset of iron death via GPX4/ROS under the NETs activation." (PMID 39108751, 2024). "Thus, enhancing GPX4 at the initiation of asthma exacerbation might prevent ferroptosis and alleviate asthma." (PMID 32685102, 2020). "Therapeutically, we highlight novel strategies such as inhaled GPX4 mRNA nanocarriers and ALOX15 inhibitors, underscoring the potential of targeting this axis for precision medicine in refractory asthma." (PMID 41573584, 2025). "According to this study, ferroptosis has a role in the pathophysiology of OVA-induced asthma, as evidenced by the elevation of iron, oxidative DNA damage, and MDA levels and the downregulation of the antioxidant protein GPx4." (PMID 39305381, 2025). "By upregulating GPX4, METTL3 inhibits ferroptosis in bronchial epithelial cells, which promotes cell survival, proliferation, and alleviates asthma symptoms." (PMID 41008562, 2025).
asthma (continued). "SC remarkably facilitated the protein expression of FTH1 (P<0.05) and GPX4 (P<0.01), and suppressed the MDA and Fe2+ levels in the asthma cell model (P<0.05) compared with the model group." (PMID 37970439, 2023). "Consistently, the expression of SLC7A11, SLC3A2, and GPX-4 was also inhibited, while the level of ALOX5 was enhanced in lung tissues of asthma mice or IL-13-stimulated BEAS-2B cells, further demonstrating the initiation of ferroptosis during the development of asthma." (PMID 35154576, 2022). "The downregulation of antioxidant proteins (SLC7A11 and GPX4) and the upregulation of toxic derivatives (4-HNE and MDA) shown in the OVA group in this study demonstrates that ferroptosis signaling is involved in OVA-induced asthma pathogenesis." (PMID 36290772, 2022). "However, whether GPX-4 and GSH could alleviate asthma by relieving ferroptosis is unclear." (PMID 35154576, 2022).